TNF (tumor necrosis factor)
Diseases named in the same sentence as TNF in open-access papers (continued):
Sharing a sentence is not in itself a finding about the gene and the disease.
pterygium (12 papers, 2011 to 2025). A wedge-shaped fibrovascular lesion arising from the bulbar conjunctiva and extending to the cornea. "The researchers emphasized the need for future studies to investigate other polymorphisms or haplotypes of TNF-α and IL-1β to better assess genetic susceptibility to pterygium formation and recurrence." (PMID 39682531, 2024). "Based on the DEG analysis comparing with the 2D control, the 3D pterygium models showed consistent upregulation of genes correlated to interleukin cascade, tumor necrosis factor (TNF) signaling, and other inflammatory responses." (PMID 35101743, 2022). "In accordance, levels of inflammatory cytokines such as IL-6, IL-8 and tumor necrosis factor-α (TNF- α) are increased in pterygium." (PMID 36555331, 2022). "GSEA revealed that the 3D pterygium model expressed enriched gene hallmarks of TNF-α/NF-κB signaling, EMT, and EGF signaling, while the controls showed enrichment involved in epithelial differentiation and keratinization." (PMID 35101743, 2022). "The GSEA and GO enrichment analysis indicated that the hCjSCs in the 3D pterygium model were under ER stress and DNA damage, which were potentially induced by the inflammatory stimulus through TNF-α/NF-κB signaling and interleukin cascade." (PMID 35101743, 2022). "In this way, increases in the interleukins IL-1, IL-6, and IL-8 and the tumor necrosis factor TNF-α have been described as contributing to the recruitment of other inflammatory mediators and metalloproteases involved in pterygium pathogenesis." (PMID 34945227, 2021). "Next, the effect of MMC injection on the expression of inflammatory factors including TGF-β1, VEGF, IL-6, IL-8, and TNF-α that have been reported to be highly expressed in pterygium tissues were also evaluated." (PMID 31827916, 2019). "The dichloromethane extract of S. dendroideum promoted corneal healing in a murine model of pterygium-like eye lesions and exhibited immunomodulatory effects by reducing the levels of pro-inflammatory cytokines TNF-α and IL-1α, maintaining the expression of the anti-inflammatory cytokine IL-10." (PMID 37895904, 2023). "Gene expression analysis revealed significant overexpression of inflammatory genes in the pterygium, with differences up to 24.7-fold for IL17A (p < 0.05) and 2.8-fold for TNF-α (p < 0.05) compared to healthy conjunctiva." (PMID 40806545, 2025). "Other downregulated pathways (e.g., tumor necrosis factor (TNF) signaling, mitogen-activated protein kinase (MAPK) signaling, and transcription factor) have strong relationships with UV radiation or pterygium." (PMID 36187094, 2022). "Several studies have documented the expression of cytokines, such as tumor necrosis factor (TNF), basic fibroblast growth factor (bFGF), transforming growth factor (TGF), and platelet-derived growth factor (PDGF) in pterygia and cultured pterygium cells." (PMID 21270971, 2011). "UV-inducible cytokines generated by the pterygium epithelium, such as interleukins and tumor necrosis factor (TNF)-α, may contribute to the initiation of neovascularization and chronic inflammation during pterygium formation." (PMID 28068383, 2017). "Although previous studies suggest that CsA prevents the synthesis and secretion of interleukins and TNF-α, and blocks VEGF-induced angiogenesis, the mechanisms involved in CsA-mediated inhibition of MMP expression and pterygium fibroblast migration have not been completely elucidated." (PMID 28068383, 2017).
pustular psoriasis (12 papers, 2008 to 2025). "Pustular psoriasis exacerbated/induced by ICIs may follow the same pathogenic route as pustular psoriasis experienced by patients receiving TNF-α inhibitors." (PMID 38541099, 2024). "Studies suggest that TNF-alpha inhibition can paradoxically enhance interferon-alpha activity, leading to the development of pustular psoriasis in some cases." (PMID 40546629, 2025). "TNF-alpha in pustular psoriasis works by promoting an overall inflammatory response and recruiting neutrophils to induce the formation of pustules, which further contributes to disease pathology." (PMID 40546629, 2025). "TNF-alpha inhibitors should be discontinued if pustular psoriasis develops, with IL-23 inhibitors providing a viable alternative." (PMID 40546629, 2025). "If pustular psoriasis develops, cessation of TNF-alpha inhibitor therapy is imperative in reversing symptoms, and alternative treatments should be pursued." (PMID 40546629, 2025). "While TNF-alpha inhibitors like adalimumab reduce inflammation, paradoxical reactions like pustular psoriasis are a well-documented sequela that can occur due to enhanced interferon-alpha activity." (PMID 40546629, 2025). "While TNF-alpha inhibitors like adalimumab reduce inflammation, paradoxical reactions like pustular psoriasis can occur due to enhanced interferon-alpha activity." (PMID 40546629, 2025). "Their analysis highlighted cases of dramatic clinical improvement, including patients with severe pustular psoriasis achieving near-complete remission after Lactobacillus sporogenes supplementation and significant TNF-α reduction following Bifidobacterium infantis administration." (PMID 41304102, 2025). "Interestingly, case reports have indicated that different types of IL-17A inhibitors can induce pustular psoriasis, which is a well-known rare paradoxical reaction of anti TNF-α therapies." (PMID 38695018, 2024). "Additionally, treatment with dapsone and acitretin has been successfully used in patients with pustular psoriasis and can be considered when patients have eruptions induced by TNF inhibitors." (PMID 39781163, 2024). "In a previous report, in a set of five patients with pustular psoriasis, depletion of CD14+CD16+ circulating monocytes ameliorated symptoms and, interestingly, no change in TNF was observed, what suggests that other factors produced by monocytes may play a role in the pathogenesis of the disease." (PMID 32269570, 2020).
stenosis (12 papers, 2013 to 2026). "In addition, both LIMK1 and TNFα are associated with cardiac stenosis, while TNFα is specifically associated with cardiac stress response, inflammation, and fibrosis." (PMID 23518061, 2013). "After the treatment with anti-tumor necrosis factor-α agent, the ulceration markedly improved with development of severe colonic stenosis, which was successfully dilated with endoscopic balloon dilation." (PMID 38349435, 2024). "Due to the lack of sufficient evidence and individual risk stratification tools favoring this approach, patients with bowel strictures are alternatively managed by surgical resection; therefore, more studies are needed to evaluate the use of anti-TNF-α therapy in this patient group." (PMID 33052277, 2020). "Furthermore, the clinical course of IBD in some of these cases seems to be severe, with two patients reported to have developed bowel stenosis requiring a partial colectomy and another patient needing anti-TNF therapy following similar IBD-related complication." (PMID 29163546, 2017). "We aimed to assess the effectiveness of the combined therapy with anti‐TNFα and EBD in preventing intestinal stricture recurrence and surgery in patients with CD." (PMID 32514466, 2020). "According to our results, the combined therapy with anti‐TNFα and EBD would have preventive effects on intestinal stricture recurrence in hospitalized patients with severe CD." (PMID 32514466, 2020). "However, a number of studies suggest that patients with a non-stricturing CD phenotype that initially respond to anti-TNF-α therapy also report significant rates of intestinal strictures and obstructions." (PMID 33052277, 2020). "While TNF-α or IL-6-receptor inhibitors therapy was reported to reduce the production of PTX3, reflecting vascular inflammation and progression in TAK patients, IL-6-receptor antibody improved neither vascular stenosis nor thickness nor PTX-3 level." (PMID 33529185, 2021).
thalassemia (12 papers, 2009 to 2026). An inherited blood disorder characterized by a decreased synthesis of one of the polypeptide chains that form hemoglobin. "Thalassemia patients are more prone to infections, and TNF-α reduces lipoprotein lipase activity in adipose tissue." (PMID 39328659, 2024). "The 2-h monocyte-derived TNF-α expression fold-change after stimulation with LPS analyzed using qRT-PCR technique was significantly lower in all thalassemia groups with overall between-group p < 0.0001." (PMID 36323999, 2023). "On the other hand, in thalassemia patients also observed aspect a reduction in leptin partly due to the genetic defect This possibility is suggested that TNF and IL6 affect leptin much more than pituitary- hypothalamus axis." (PMID 24575288, 2013). "As the study groups were patients with major thalassemia and it plays a role in the pathophysiology of thalassemia inflammation, it leads to an increase in TNF and IL6." (PMID 24575288, 2013). "Similarly, the 2-h TNF-α level measured by sandwich ELISA assay was significantly decreased in all thalassemia groups with an overall between-groups p < 0.0001." (PMID 36323999, 2023). "TNF-α and IL-10 were found to be elevated in iron overloaded patients with thalassemia major." (PMID 25822525, 2015). "Similarly, the mean 2-h TNF-α level measured by sandwich ELISA assay was significantly lower in all thalassemia groups, at 98.16 pg/mL in controls, versus 56.45 pg/mL (p = 0.0093) in NTDT, 39.05 pg/mL (p = 0.0001) in TDT-NS and 32.37 pg/mL (p < 0.0001) in TDT-S." (PMID 36323999, 2023). "Serum 8-isoprostane, TNF-alpha, IL-10, 24-hour ECG monitoring, echocardiograms and the incidence of thalassemia-related complications were collected." (PMID 32547310, 2020). "The results showed that basal levels of granulocyte–macrophage colony-stimulating factor (GM-CSF) and also TNF-α production in thalassemia patients were significantly lower than non-thalassemia individuals." (PMID 36323999, 2023). "Also, Butthep et al13 reported that thalassemia patients are characterized by increased levels of VEGF and TNF." (PMID 23795282, 2013). "Iron chelation augments tumor necrosis factor alpha (TNF-α), GM-CSF and IFN-γ release from monocytes/macrophages in thalassemia patients irrespective of ferritin levels." (PMID 32117626, 2020).
aortic stenosis (11 papers, 2012 to 2026). Aortic valve stenosis is a aortic valve disease caused by the incomplete opening of the aortic valve. "Unlike IGF1 and PPARγ, SRA co-activation negatively regulates Toll-like-recptor 4 (Tlr4) and subsequent TNFα release, both of which have been linked to the pro-inflammatory response in the early stages of atherosclerosis and aortic stenosis." (PMID 34805273, 2021). "The gradual decrease of TNF-α after TAVI supports the hypothesis of an underlying subclinical inflammation in patients with severe aortic stenosis." (PMID 41552677, 2025). "From the literature we know that pro-inflammatory markers such as Tumor necrosis factor-alpha (TNF-alpha), receptor activator of nuclear factor-kappa B (NF-κB) ligand (RANKL) and Interleukin-6 (IL-6) are associated with aortic stenosis." (PMID 27488119, 2017). "In patients with aortic stenosis, serum TNF-α level has similarly been shown to be increased compared with healthy subjects and related to functional class." (PMID 23284897, 2012). "Yet, key promoters of aortic stenosis such as TNFα, members of the Wnt-pathway, and TLR activation are modulated by ncRNA expression and thus may provide a promising target for future investigations." (PMID 34805273, 2021).
breast adenocarcinoma (11 papers, 2014 to 2025). "TNF-α is also a tumor-promoting necrosis factor in the tumor microenvironment, highly expressed in breast adenocarcinomas." (PMID 38818375, 2024). "In agreement with previous findings, the exposure of breast adenocarcinoma cells to 43 °C HS resulted in the attenuation of the immediate NF-κB signalling and gene expression response to TNFα and IL1β stimulation." (PMID 32448393, 2020). "We used a treatment protocol where breast adenocarcinoma MCF7 cells were exposed to 1 h 43 °C HS, subsequently recovered in normal conditions (37 °C) for up to 4 h and then treated with 10 ng/ml TNFα." (PMID 32448393, 2020). "For example, oestrogen receptor α (ER α) stimulated breast adenocarcinoma cells, and retinal pigment epithelial cells induced to an epithelial-to-mesenchymal transition with TGF β + TNF α displayed the opposite pattern of enrichment, i.e. longer CpG islands are enriched in early response genes." (PMID 29945659, 2018). "In addition, in the MCF-7 breast adenocarcinoma cell line, RBM5 and tumor necrosis factor alpha (TNF-α) expression were shown to be positively correlated, TNF-α being an important apoptosis regulatory factor." (PMID 26659391, 2016).
cutaneous melanoma (11 papers, 2003 to 2023). A primary melanoma arising from atypical melanocytes in the skin. "Additional cues such as TNFα (tumour necrosis factor α) and TGFβ are likely factors that induce the phenotype switch in cutaneous melanoma cells." (PMID 35682684, 2022). "In conclusion, we provide evidence that TNF-α has a dramatic effect on migration of human cutaneous melanoma cells in vitro and that α-MSH plays an important role in reducing cell migration and opposing the promigratory effects of TNF-α." (PMID 15054471, 2004). "Current available data suggest that TNF-α and interleukins IL1B, IL-6, IL-8 and IL-18 can modulate the proliferation, survival and migration of cutaneous melanoma cells." (PMID 37047539, 2023). "TNFα can also activate ATF4 and JUN, resulting in dedifferentiated cutaneous melanoma cells." (PMID 35682684, 2022). "The aim of this study was to evaluate whether Saccharomyces cerevisiae-derived zymosan-modulated skin melanoma progression by regulation of TLR-2 and TLR-4 expression in peritoneal macrophages and serum TNF-α level." (PMID 29588627, 2018). "Consequently, we validated our previous pilot study in a large and independent patient cohort, using standard FFPE tissue sections instead of cryosections, and confirmed the role of CCL20, TNF, and VEGFA expression by TAMs in predicting clinical behavior of primary cutaneous melanoma patients." (PMID 34439098, 2021).
gallstones (11 papers, 2016 to 2025). Solid crystalline precipitates in the biliary tract, usually formed in the gallbladder, resulting in the condition of cholelithiasis. "The etiology of AP, whether due to gallstone or other, was also associated with changes in cytokine concentration, namely, IL-8 and TNF-alpha, which showed increased levels at T1 in patients with gallstone as the AP cause." (PMID 38673560, 2024). "Previous studies indicated increased cholesterol levels could induce the expressions of inflammatory factors such as interleukin (IL)-1, IL-6, and tumor necrosis factor-alpha, which could cause cholecystitis and induce the formation of gallstones." (PMID 32011459, 2020). "Lastly, inflammatory mediators released by adipose tissue, such as TNF-α and IL-6, can intensify metabolic dysregulation and abnormal cholesterol metabolism, facilitating gallstone development." (PMID 41287115, 2025). "Higher DII scores are also associated with the production of higher concentrations of TNF-α, IL-6, CRP, and a range of other factors that contribute to greater gallstone risk." (PMID 38779446, 2024). "Chronic inflammation induced by gallstones, infection, or other factors is one of the leading causes of GBC according to epidemiological investigations, and TNF-α has been detected in the inflammatory environment of the gallbladder." (PMID 26992854, 2016). "In addition, our study indicated that some TNF-related CICs were the accelerative factors of asymptomatic gallstone." (PMID 40068083, 2025). "In addition, inflammatory factors such as TNF-α can promote the expression of mucins, contributing to gallstone formation." (PMID 39867880, 2024). "Furthermore, future studies should incorporate a broader panel of inflammatory and metabolic markers, such as interleukins, tumor necrosis factor-alpha (TNF-α), adiponectin, and lipid profiles, to disentangle the causal pathways underlying the AGP-gallstone association." (PMID 40013166, 2025). "Gallstones can not only induce cellular stress, but they can also disturb the epithelial barrier, releasing epitheliocyte contents in the extracellular space, thus inducing TNFα and IL-6 expression in immune cells, as well as acute phase protein synthesis by binding to hepatocytes." (PMID 34449702, 2021).
gastric disease (11 papers, 2013 to 2025). "Polymorphisms in the tumor necrosis factor α (TNF-α) gene are emerging as key determinants of gastric diseases." (PMID 30413607, 2018). "Polymorphisms in tumor necrosis factor alpha (TNF-α) gene are emerging as key determinants of gastric diseases." (PMID 26504356, 2015). "The aim of our study was to associate TNF-α polymorphism to the high risk of gastric diseases." (PMID 26504356, 2015). "Inflammatory cytokines, IL-6 and TNF-α, play a pathogenic role in diseases of the stomach." (PMID 25187847, 2014). "The inflammatory cytokines IL-6 and TNF-α play pathogenic roles in diseases of the stomach." (PMID 24137202, 2013). "TNF-α-308 G > A (rs1800620), one of the most frequently studied polymorphisms on this gene, seems to have an influence on transcriptional activities and may contribute to the development of gastric disease." (PMID 26719751, 2015). "Curcumin inhibits nuclear factor (NF)-κB and reduces gastric mucosal damage in rats suffering from NSAID-induced gastropathy, leukocyte adhesions, intercellular adhesion molecule 1, and tumor necrosis factor (TNF)-α." (PMID 35401176, 2022). "Cytokine receptors and the inflammatory cytokines IL-6, IL-12, TNF-α and IFN-γ play a pathogenic role in gastric disease." (PMID 25187847, 2014). "Cytokine receptors and the inflammatory cytokines, IL-6, IL-12, TNF-α and IFN-γ, play pathogenic roles in gastric disease." (PMID 25120640, 2014). "TNF-α contributes to gastropathy induced by Helicobacter pylori, alcohol consumption and NSAIDs, with studies carried out on NSAID-treated rats showing that it can increase the expression of adhesion molecules, regulate apoptosis in gastric epithelial cells, and promote neutrophil adherence." (PMID 36292625, 2022). "Likewise, genistein has been shown to reduce the levels of malondialdehyde and TNF-α in a rat model of indomethacin-induced gastropathy." (PMID 33297977, 2020). "In addition, we found that, contrary to results reported in the literature, TNF-α-308 G > A polymorphisms did not influence TNF-α mRNA expression in cases of gastric disease." (PMID 26719751, 2015).
generalized anxiety disorder (11 papers, 2020 to 2026). An anxiety disorder characterized by excessive and difficult-to-control worry about a number of life situations. "For example, significantly elevated levels of CRP, IFN-γ and TNF-α were found in patients with Generalized Anxiety Disorder (GAD) compared with healthy controls." (PMID 39624485, 2024). "Increased tumor necrosis factor alpha levels have also been reported in generalized anxiety disorder patients, and genetic studies have reported patients with generalized anxiety disorder show alterations in immune-related gene expression." (PMID 32906843, 2020). "CRP levels in blood, serum or plasma samples was significantly raised in generalized anxiety disorder (GAD) patients by meta-analysis, and IFN-γ and TNF-α levels were significantly increased in at least two or more studies." (PMID 34440101, 2021).